PYY3 (peptide YY 3 (pseudogene))
Synonyms: OTTHUMG00000021515
Gene: Processed pseudogene on chromosome X (50,156,159 to 50,156,371, forward strand). Ensembl gene ENSG00000181977.
Subcellular location: Secreted
Diseases named in the same sentence as PYY3 in open-access papers:
PYY3 is named in the same sentence as 12 diseases in open-access papers, as found by Europe PMC text mining. Sharing a sentence is not in itself a finding about the gene and the disease. The quoted sentences say what the papers report.
Obesity (9 papers, 2014 to 2025). Accumulation of substantial excess body fat. "Almost all studies report that PYY3–36 exhibits both anti-obesity and insulin-sensitizing properties, making it a promising candidate for T2D management." (PMID 41228539, 2025). "A substantial and growing body of preclinical evidence has examined the metabolic actions of PYY, particularly the PYY3–36 isoform, in rodent models of obesity and insulin resistance." (PMID 41228539, 2025). "In summary, PYY3–36 plays an essential role in mediating satiety and appetite regulation, with potential applications in the treatment of obesity and related metabolic disorders." (PMID 41155711, 2025). "Using a controlled study design, we have demonstrated the promising potential of the combined regime (liraglutide+PYY3-36) as an alternative to RYGB in the treatment of obesity, as shown in a previous publication and as summarized in the introduction." (PMID 35160204, 2022). "An N-terminally degraded metabolite, PYY3–36, has anorexigenic effects, which makes the PYY system a target for obesity treatment." (PMID 26197931, 2015). "If low-dose combinations of PYY3–36 and GLP-17–36 amide are to be used as future treatments for obesity and/or diabetes, it is important to establish their effects on glucose homeostasis." (PMID 25144632, 2014). "Here we show that attaching a fatty acid to the obesity-drug relevant peptide PYY3-36 is not sufficient for long pharmacokinetics (PK), since the position in the backbone, but also type of fatty acid and linker strongly influences PK and potency." (PMID 34707178, 2021). "Importantly, we have shown that the combination of GLP-1 and PYY3–36 retains the glucose-lowering insulinotropic effect observed with GLP-1, which adds further support to the concept of multiple gut hormone therapy as a treatment for diabetes and obesity." (PMID 25144632, 2014).
Insulin resistance (2 papers, 2024 to 2025). Increased resistance towards insulin, that is, diminished effectiveness of insulin in reducing blood glucose levels. "Small-scale studies in overweight or obese populations have reported that acute infusion of PYY3–36 can lead to modest improvements in oral glucose tolerance and Homeostatic Model Assessment of Insulin Resistance (HOMA-IR)." (PMID 41228539, 2025).
alcohol-use disorder (1 paper, 2024). "In contrast to ghrelin’s effects, PYY3–36 and GLP-1 have been associated with the decreased activation of brain reward areas in response to food- and alcohol-related cues in heathy controls and obese and diabetic patients and patients with alcohol-use disorder." (PMID 39200325, 2024).
Anorexia (1 paper, 2022). Lack of desire to eat (loss of appetite). "This is in accordance with our previous research that DON selectively activated CaSR and elevated hormones CCK and PYY3–36 to mediate anorexia." (PMID 35737050, 2022).
esophageal cancer (1 paper, 2023). A primary or metastatic malignant neoplasm involving the esophagus. "PYY also blocked the growth of hepatic carcinoma/prostate cancer cells and decreased tumor volume/weight, and PYY3-36 inhibited the growth of esophageal cancer cell lines by inducing apoptosis." (PMID 37373115, 2023). "PYY3-36 blocked the growth of Barrett’s esophageal cancer cell lines (BIC, SEG-1)." (PMID 37373115, 2023).
mental disorder (1 paper, 2024). A disease that has its basis in the disruption of mental process. "For example, full-length PYY binds with similar affinity to all Y receptors, but the predominant circulating form of PYY-immunoreactivity, truncated PYY3–36, preferentially binds to the Y2 receptor, a G protein-coupled receptor implicated in appetite and feeding control, mood, and mental disorders." (PMID 38961511, 2024).
Renal failure (1 paper, 2006). "Renal failure is known to be associated with high levels of PYY, and it is currently unclear whether this represents the active PYY3–36." (PMID 16420657, 2006).
PYY3 also shares sentences with these, for which no sentence is quoted: diabetes (1 paper); diverticulitis (1); liver steatosis (1); Nausea (1); steatosis (1).